RCHY1 (ring finger and CHY zinc finger domain containing 1)
Description:
Catalyzes monoubiquitinates the translesion DNA polymerase POLH. Involved in the ribosome-associated quality control (RQC) pathway, which mediates the extraction of incompletely synthesized nascent chains from stalled ribosomes: RCHY1 acts downstream of NEMF and recognizes CAT tails associated with stalled nascent chains, leading to their ubiquitination and degradation. [Isoform 4]: Has no E3 ubiquitin-protein ligase activity.
Synonyms: ARNIP; CHIMP; PIRH2; RNF199; ZNF363; DKFZp586C1620; PRO1996; ZCHY
Tractability: PROTAC: UniProt records ubiquitination sites on it; ubiquitination databases record sites on it; its protein half-life has been measured.
Gene: Protein-coding gene on chromosome 4 (75,479,033 to 75,514,764, reverse strand). Ensembl gene ENSG00000163743.
Subcellular location: Nucleus; Nucleus speckle; Cytoplasm
Subcellular location (Human Protein Atlas): Cytosol; Nucleoplasm; Vesicles
Pathways (Reactome):
DNA Repair: Translesion Synthesis by POLH
Immune System: Antigen processing: Ubiquitination & Proteasome degradation
Metabolism of proteins: Ribosome Quality Control (RQC) complex extracts and degrades nascent peptide
Gene Ontology:
Molecular function: protein binding; protein homodimerization activity; ubiquitin protein ligase activity; zinc ion binding; ubiquitin-protein transferase activity
Biological process: positive regulation of proteasomal ubiquitin-dependent protein catabolic process; protein ubiquitination; rescue of stalled ribosome; ubiquitin-dependent protein catabolic process; error-free translesion synthesis
Cellular component: cytoplasm; cytosol; nuclear speck; nucleoplasm; nucleus; ubiquitin ligase complex
Genetic constraint (gnomAD): Loss-of-function variants: 10 observed, 20.44 expected, observed/expected ratio (o/e) 0.49, 90% interval 0.3 to 0.83. The upper end of that interval is the gene's LOEUF score, 0.83, which puts it in group 3 of 6, group 1 being the genes least tolerant of losing a copy. Missense variants: 139 observed, 169.16 expected, observed/expected ratio (o/e) 0.82, 90% interval 0.71 to 0.95. Synonymous variants: 44 observed, 56.72 expected, observed/expected ratio (o/e) 0.78, 90% interval 0.61 to 1.
Homologues: Orthologues: macaque RCHY1 (100% identical), chimpanzee RCHY1 (99% identical), mouse Rchy1 (90% identical), dog RCHY1 (89% identical), pig RCHY1 (89% identical), rabbit RCHY1 (86% identical), tropical clawed frog rchy1 (72% identical), zebrafish rchy1 (66% identical), Drosophila melanogaster Rchy1 (48% identical).
Diseases named in the same sentence as RCHY1 in open-access papers:
RCHY1 is named in the same sentence as 46 diseases in open-access papers, as found by Europe PMC text mining. Sharing a sentence is not in itself a finding about the gene and the disease. The quoted sentences say what the papers report.
viral infection (3 papers, 2014 to 2022). "For example, over half of these genes have been previously associated with viral infection or replication, or have been found to physically interact with viral proteins (e.g. CLDN3; CRHR2; ILF2; ILF3; LTF; miR-122; RCHY1; and, RUVBL2)." (PMID 25079789, 2014).
kidney failure (2 papers, 2011 to 2022). An acute or chronic condition that is characterized by the inability of the kidneys to adequately filter the blood. "Ring finger and CHY zinc finger domain containing 1 (RCHY1) was associated with many comorbidities, including COPD, cerebrovascular disease, renal failure, ischemic heart disease, liver disease, and pneumonia, as well as the genetic risks of psoriasis, heart failure, and coronary artery disease." (PMID 35903362, 2022).
cancer (21 papers, 2009 to 2025). A tumor composed of atypical neoplastic, often pleomorphic cells that invade other tissues. "However, despite its crucial role in cancer and other pathologies, only two physiological factors have been reported to negatively regulate RCHY1 at the protein level: RCHY1 itself and calmodulin-dependent protein kinase II (CaMKII)." (PMID 24244684, 2013).
tumor (20 papers, 2009 to 2025). "In addition, new tumor event after initial treatment, pathology tumor size stage, the expression level of RCHY1 and KDF1 might also be associated with lymphatic metastasis." (PMID 34343214, 2021). "Previous studies have described the recruitment of USP28 by the E3 ubiquitin ligases kelch-like family member 2 (KLHL2) and ring finger and CHY zinc finger domain containing 1 (RCHY1), but little is known about how these factors are affected by tumor hypoxia." (PMID 35326457, 2022).
RCHY1 also shares sentences with these, for which no sentence is quoted: breast cancer (7 papers); prostate carcinoma (6); lung carcinoma (5); hepatocellular carcinoma (4); myeloma (3); non-small cell lung carcinoma (3); sarcoma (3); gastric cancer (2); head and neck squamous cell carcinoma (2); lung adenocarcinoma (2); ovarian carcinoma (2); Alzheimer disease (1); cardiovascular diseases (1); cerebrovascular disease (1); cognitive decline (1); coronary artery disease (1); epilepsy (1); germ cell tumor (1); glioblastoma (1); glioma (1); heart failure (1); HIV-1 infection (1); infection (1); leukaemia (1); liver disease (1); lung neoplasm (1); lung squamous cell carcinomas (1); Lymphadenopathy (1); lymphoproliferative disorder (1); multiple myeloma (1).
A further 12 diseases each share a sentence with RCHY1 in 1 paper.